IL6 (interleukin 6)
Diseases named in the same sentence as IL6 in open-access papers (continued):
Sharing a sentence is not in itself a finding about the gene and the disease.
Sepsis (continued). "Indeed, overproduction of circulating levels of IL-6, TNFα, and IL-10 were accompanied by the development of hypothermia during different animal models of sepsis." (PMID 40534875, 2025). "While TNF-α and IL-6 are established mediators of the septic cascade the stronger modulation of IL-40 in our study supports its potential role as a novel biomarker of disease activity and treatment response in sepsis." (PMID 41196905, 2025). "Several studies have demonstrated that aptamer-based biosensors match or exceed antibody-based systems in sensitivity, often reaching femtomolar or even attomolar detection limits for sepsis-related biomarkers, such as IL-6, CRP, and tumor necrosis factor-alpha (TNF-α)." (PMID 40710052, 2025). "Furthermore, functional experiments demonstrated that suppression of SFT2D1 significantly reduced the expression of inflammatory cytokines CXCL10 and IL-6, suggesting its potential role in modulating the inflammatory response in sepsis." (PMID 40370519, 2025). "We conclude that AKI contributes to increased circulating IL-6 in sepsis via mtDNA release." (PMID 41355794, 2025). "As mentioned in previous related reviews, the presence of these cytokines, especially IL-6, may provide important clues for the development of sepsis." (PMID 40072101, 2025). "While IL-6 is a central mediator of hyperinflammatory responses and a well-established marker in syndromes such as sepsis, CRS, and HLH, growing evidence indicates that its prognostic capacity is enhanced when analyzed within a multi-cytokine context rather than in isolation." (PMID 41155261, 2025). "Additionally, interleukin-6 (IL-6) has emerged as a reliable biomarker of sepsis due to its sustained elevation in circulation, correlating with disease severity and mortality." (PMID 40265185, 2025). "While circulating IL-6 levels are as low as 1–5 pg/mL under homeostatic settings, they may increase by over 1,000 times during inflammatory states, and in severe situations that result in sepsis, IL-6 levels as high as μg/mL have been seen." (PMID 39963155, 2025). "Similarly, mRNA levels of proinflammatory mediators, including TNF-α, IL-1β, and IL-6, were upregulated in the lung tissue following sepsis." (PMID 40421173, 2025). "We have summarized the interactions of IL-6 related signaling pathways and sepsis." (PMID 39891057, 2025). "For instance, cytokines such as TNF-α and IL-6, produced during sepsis, play a key role in organizing inflammatory responses and may indirectly support tumor formation." (PMID 40028316, 2025). "TNF-alpha and IL-6 are two major inflammatory cytokines that are elevated in patients with bacteremia and sepsis, and their production by the innate immune system in response to bacterial infection is likely a major driver of the general inflammatory responses observed." (PMID 39835799, 2025). "In sepsis, DPEP2 is closely related to macrophage function, and its deficiency leads to excessive production of pro-inflammatory factors (such as TNF-α and IL-6), highlighting its importance in inhibiting macrophage overactivation and maintaining immune homeostasis." (PMID 41359645, 2025). "Additionally, the antagonist CID16020046 significantly decreases the production of pro-inflammatory cytokines TNF-α and IL-6 and reduces leukocyte adherence in the submucosal venules of the intestines during experimental sepsis." (PMID 40429822, 2025). "Estrogen is known to exert protective effects against sepsis by modulating immune responses, acting primarily as an anti-inflammatory agent that dampens the expression of proinflammatory cytokines such as IL-6 and TNF-α, which are typically elevated during septic episodes." (PMID 41318782, 2025). "Therefore, in patients with malignancy, it is crucial to monitor the inflammatory status after sepsis and consider using molecular-targeted therapies, such as tocilizumab, for elevated IL-6 levels." (PMID 40136690, 2025).
Sepsis (continued). "The beneficial effects of A12 are not limited to sepsis, as it was also successful in an intestinal ischemia reperfusion model demonstrating that treatment with A12 significantly reducing serum IL-6, organ injury markers, lung injury scores, and survival vs. vehicle treatment." (PMID 39838468, 2025). "Blood IL-6 levels were significantly associated with mortality in non-elderly patients with sepsis, but not in elderly patients." (PMID 39800741, 2025). "We hypothesise that the IL-6/PCT ratio, as a novel biomarker, will improve diagnostic accuracy in distinguishing sepsis from CRS in CAR-T recipients." (PMID 41347097, 2025). "Morphological changes in activated leukocytes depicted through leukocyte cell population data (CPD) could be viewed as an even earlier biomarker than the biochemical early biomarkers of sepsis such as IL-6." (PMID 40142279, 2025). "We hypothesized that IL-6 values would significantly differ between sepsis and NEC, and between medical and surgical NEC, adding new valuable insights for timely and tailored clinical interventions to the existing knowledge." (PMID 39958363, 2025). "The previous study of our research group confirmed that DCHD significantly could reduce serum inflammatory factor levels (e.g., IL-1β, TNF-α, IL-6) in rats with sepsis induced by cecal ligation and puncture." (PMID 41378216, 2025). "According to the Kaplan–Meier analysis, the median ICU survival (overall survival) was 19 days in the overall cohort (95% confidence interval (CI) 15–26 days), and not statistically different between patients with high (≥200 pg/mL) or low (<200 pg/mL) levels of IL-6 or diagnosis of sepsis." (PMID 41155261, 2025). "In the central nervous system, agents like exedin-4 and liraglutide reduce neuroinflammation by inhibiting microglial activation and cytokine production (IL-1β, IL-6, TNF-α), while preserving neuronal integrity and preventing cognitive dysfunction associated with sepsis." (PMID 41357527, 2025). "Considering the heterogeneity of sepsis, the univariate Cox regression analysis showed age (p = 0.041), abdominal infection (p = 0.042), interleukin‐6 (IL‐6) (p = 0.02), SOFA score (p = 0.036), and moCD38 (p = 0.015) might be predictors of 28‐day mortality." (PMID 40145840, 2025). "While there has been limited research on laminarin in the context of sepsis, this study demonstrated that laminarin was effective in improving pulmonary edema, increasing the survival rate of mice induced by LPS, and inhibiting the levels of IL‐6, a biomarker of sepsis, in the serum of septic mice." (PMID 40045157, 2025). "IL-6 and IL-8 are very tightly correlated: R2 0.95 in our cohort of sepsis patients." (PMID 40433392, 2025). "However, the efficacy of TCZ in sepsis remains controversial and appears to be strongly influenced by the timing of administration, reflecting the complex and ambivalent role of IL-6 in sepsis pathophysiology." (PMID 41268545, 2025). "For example, IL-6 has been shown to influence hepatic lipid accumulation, and previous work has demonstrated that fluoxetine can drive hepatic triglyceride accumulation in non-sepsis contexts." (PMID 39951524, 2025). "A study involving critically ill patients including both with and without sepsis demonstrated that baseline plasma IL-6 levels were associated with the need for future organ support therapies, such as vasopressors/inotropes and renal replacement therapy." (PMID 39800741, 2025). "A study with a small sample size (n = 142), including adult patients of all ages with sepsis or SIRS (median age [range], sepsis vs. SIRS, 75 vs. 68 years), suggested that increased serum IL-6 levels were associated with an increased risk of 28-day mortality (HR = 1 pg/mL change, 1.0004)." (PMID 39800741, 2025).
Sepsis (continued). "Although this correlation has been previously observed in various settings involving plasmatic IL6 levels in sepsis and in intraamniotic fluid, we found that ELISA and Cobas were also comparable for measuring IL6 in a readily available respiratory matrix in preterm infants at risk of developing BPD." (PMID 40173116, 2025). "In this sense, 0.1 mM acetic acid decreases IL-6 and TNF-alpha production in the liver of mice with cecal ligation and puncture-induced sepsis, whereas 20 mM acetic acid stimulates IL-6, IL-8, and IL-1 beta synthesis in peripheral blood mononuclear cells (PBMCs) from healthy donors." (PMID 41383632, 2025). "However, studies have shown that IL‐6 is only moderately effective in differentiating between sepsis and non‐sepsis." (PMID 39745136, 2025). "Among these cytokines, IL-6 is a key biomarker and prognostic indicator of sepsis." (PMID 40718494, 2025). "The pathogenesis of sepsis involves the initial excessive activation of the immune system, resulting in the release of pro-inflammatory cytokines such as Interleukin-1 beta (IL-1β), Interleukin-6 (IL-6) and Tumor Necrosis Factor-alpha (TNF-α)." (PMID 40688672, 2025). "Moreover, data from the literature suggest that the presence of elevated IL-6 levels in neonates with early onset sepsis is related to blood sampling within the first 24 h of life." (PMID 39940970, 2025). "Interleukin-6 (IL-6) has been studied as an early marker of sepsis and AKI." (PMID 40142279, 2025). "Recently, HMGB1 has been identified as a late-phase inflammatory mediator in sepsis, persisting during prolonged inflammation and contributing to poor outcomes, while cytokines such as IL-6 act as early-phase mediators and play a key role in the cytokine storm associated with BM." (PMID 39849347, 2025). "Prolonged IL-6 elevation in septic patients implies a broader therapeutic window for IL-6 blockade compared to other cytokines, positioning it as a novel strategy for severe sepsis and septic shock." (PMID 41256846, 2025). "For instance, IL-6 activates STAT3 that initially provides anti-inflammatory protection in sepsis, but its prolonged activation may contribute to immune paralysis." (PMID 41041277, 2025). "Our observation that the highest dose of sodium ascorbate (3.0 g/kg) reduced the renal medullary NF-κB levels may, in part, explain our previous finding that sodium ascorbate attenuated the sepsis-induced rise in plasma IL-6." (PMID 41457243, 2025). "Second, through anti‐inflammatory and immunomodulatory effects: β‐blockers suppress the nuclear factor‐κB pathway, leading to decreased release of pro‐inflammatory cytokines (e.g., TNF‐α, IL‐6) and alleviating sepsis‐induced cytokine storm‐mediated myocardial injury." (PMID 41324108, 2025). "Although these studies demonstrate that both NUTRIC and mNUTRIC scores are effective in predicting prognosis in sepsis patients, we argue that IL-6 should not be entirely excluded from nutritional risk assessment." (PMID 40823032, 2025). "Administering serum EVs derived from a mouse model of sepsis produced by lipopolysaccharide (LPS) enhanced the microglial cell activation, the proliferation of astrocytes, and elevated production of IL‐6 and TNF‐α in the hippocampus and cerebral cortex of healthy mice." (PMID 40537921, 2025). "Additionally, this study demonstrated significant correlations between resistin, S100A8/A9, CRP, and IL-6 in sepsis patients." (PMID 40568710, 2025). "Notably, inflammatory cytokines including TNF-α, IL-1β, and IL-6 serve as critical regulators in sepsis pathogenesis." (PMID 40775729, 2025). "Therefore, this study aimed to investigate the effects of cetirizine and dexamethasone (alone and in combination) on serum levels of MaR-1, TNF-α, IFN-γ, IL-1, IL-2, IL-6, IL-8, and IL-10 in a rat model of sepsis induced by CLP method." (PMID 41517447, 2025).
Sepsis (continued). "Inflammatory biomarkers such as neutrophil CD64, IL-6, and PCT have also shown diagnostic value in infectious conditions like sepsis and may reflect the systemic inflammatory response that accompanies SAP with IAI." (PMID 40852356, 2025). "A key complicating factor is the wide variability in IL-6 levels observed in sepsis." (PMID 40149943, 2025). "Notably, the dichotomy between classic and trans-signalling pathways of IL-6 not only modulates the trajectory of disease progression but also delineates a critical avenue for targeted interventions in sepsis." (PMID 41300951, 2025). "The development of AKI in sepsis patients was strongly associated with RDW, APACHE II score, and the biomarkers PCT, IL-6, CRP, and cystatin C. After the intervention, the incidence of AKI and AKI grade 3 significantly decreased, along with lower rates of renal replacement therapy and mortality." (PMID 41281283, 2025). "Elevated levels of biomarkers such as serum amyloid A (SAA), sTREM-1, mannan, anti-mannan antibodies, interleukin-6 (IL-6), interleukin-8 (IL-8), MCP-1, presepsin, and suPAR have been linked to sepsis and are commonly used for early diagnosis and prognostic evaluation." (PMID 40870363, 2025). "They reported that serum IL-6 could be used with high accuracy to detect sepsis in neonates with the cut-off values of 80 pg/mL on the first day of life, 40 pg/mL in the first week (days 2–7), and 30 pg/mL after seven days of life." (PMID 38535886, 2024). "Along with these changes, the mRNA levels of inflammatory mediators such as tumor necrosis factor-α (Tnf-α), chemokine ligand 2 (Ccl2), interleukin-6 (Il-6), interleukin-1β (Il-1β), and nitric oxide synthase 2 (Nos2) also demonstrated a marked elevation in the sepsis group." (PMID 38705396, 2024). "Furthermore, thermal-burn patients with a combination of elevated IL-6 and IL-12p70 concentration and decreased TNF-α at admission were found to be at a greater risk of developing and dying of sepsis." (PMID 39716257, 2024). "In the early stages of sepsis, macrophages become overactivated, resulting in an increase of pro-inflammatory M1 macrophages and the release of a large number of inflammatory cytokines (such as IL-1, IL-6, TNF-α, and iNOS)." (PMID 38715602, 2024). "Integrating IL-6 with these clinical scores may enhance the prognostic accuracy for sepsis and septic shock patients at admission to the ED." (PMID 39202614, 2024). "IL-6 and PCT have a similar, yet superior, diagnostic value for sepsis compared to CRP." (PMID 39589972, 2024). "The study determined the optimal cutoff values for sepsis and septic shock, demonstrating that IL-6 levels could effectively distinguish between the two conditions." (PMID 39201697, 2024). "Similarly, drugs that inhibit the activity of IL-1 (e.g., IL-1 receptor antagonist), IL-6, and IL-8 have also been shown to improve outcomes in patients with sepsis." (PMID 38637839, 2024). "Additionally, it would be valuable to correlate the insights derived from NEUT-RI with IL-6 levels for early sepsis diagnosis." (PMID 38667467, 2024). "Upon the onset of sepsis, AMs are activated and secrete a large number of inflammatory factors, such as tumor necrosis factor α (TNFα), interleukin-1β (IL-1β), and interleukin-6 (IL-6), triggering the inflammatory cytokine storm and tissue damage." (PMID 38725041, 2024). "Therefore, it is reasonable that IL-6 would be the targeted cytokine in severe sepsis/septic shock in children with febrile neutropenia." (PMID 38672594, 2024). "Additionally, we investigated the relationship between sTREM-1 and other essential biomarkers in sepsis, including IL-6, lactate, PCT, and CRP." (PMID 39655134, 2024). "Moreover, the elevated NGAL and KIM‐1 levels in serum, TNF‐α, IL‐6, and IL‐1β levels in the kidneys in sepsis group were partly reversed by LV‐shMALAT1." (PMID 39390627, 2024).
Sepsis (continued). "Based on the findings of this review, IL-6 might be of use for the diagnosis of late onset sepsis in populations of preterm infants when measured at the time of sepsis suspicion." (PMID 38671704, 2024). "As more evidence accumulates, we may see increased adoption of IL-6 testing in the clinical setting to improve sepsis management and patient outcomes." (PMID 39201697, 2024). "In other studies, it has been proposed that different pro-inflammatory markers such as tumor necrosis factor-α (TNF-α), interleukin (IL)-1, IL-6, and IL-8 are increased in sepsis and may lead to an increase in thrombocyte production." (PMID 39417064, 2024). "The lower IL-6 levels in our study may be due to various factors, including the early or late stages of sepsis on admission, when IL-6 peaks can be missed due to their transient nature." (PMID 39202614, 2024). "Serum IL-6 levels rapidly increased in patients with sepsis within 2 h of infection onset." (PMID 38672594, 2024). "To test our hypothesis that induction of a proper APR partly determines sepsis sensitivity, we treated mice with IL6 and DEX 12 h before CLP." (PMID 39261648, 2024). "In vivo, TRAIL-encapsulated nanogel significantly reduced TNF-α and IL-6 levels, blood bacterial load, and pulmonary leukocytes accumulation; thus, it protected mice against K. pneumoniae-induced sepsis and LPS-induced lung and kidney injury and prolonged their survival rates." (PMID 38637839, 2024). "Most studies measured IL-6 levels at the time of first signs and symptoms of sepsis." (PMID 38671704, 2024). "In vivo studies using mouse models of LPS-induced sepsis confirmed that fucoxanthin decreases the levels of inflammatory cytokines like IL-6 and IL-1β by regulating the NF-κB signaling pathway, thus suggesting its therapeutic potential against sepsis and acute inflammation." (PMID 39065808, 2024). "Also, interleukin 6 was at persistently high levels in both elderly patients (age >65 years) and elderly mice (age between 20 months and 22 months) with sepsis." (PMID 39642117, 2024). "In an experimental model of sepsis induced by cecal ligation, female mice exhibit higher survival rates and maintain splenocyte functions, whereas male mice release higher levels of IL-6, TNF-α, and prostaglandin E2 (PGE2)." (PMID 38835761, 2024). "Bacterial lipopolysaccharide (LPS) is known to be able to stimulate the production of many proinflammatory mediators and proteins, such as iNOS, TNF-α, IL-6 and COX-2, in various inflammatory cells and to cause the physiological responses of inflammation, sepsis and stroke." (PMID 38392528, 2024). "Procalcitonin and IL-6 have also been demonstrated to predict sepsis." (PMID 39338216, 2024). "This characterization stems from the unique capacity of IL-6 to both initiate pro-inflammatory reactions, potentially exacerbating conditions like sepsis, and concurrently trigger anti-inflammatory pathways, which are essential for the body’s healing and recovery processes." (PMID 39056754, 2024). "In sepsis, crucial pro-inflammatory cytokines are IL-1β, IL-6, IL-12, and IL-17." (PMID 39063011, 2024). "However, CCI was found to correlate with delirium severity when measured using the Memorial Delirium Assessment Scale (MDAS), in a study of older inpatients with infections, and this finding remained in multivariate analysis with IL-6 and sepsis." (PMID 38965032, 2024). "Overexpressed in inflammatory sites.Long‐term high‐level IL‐6 may lead to sepsis.Usually regarded as an indicator of systemic Inflammations in the clinic." (PMID 37985923, 2024). "Serum levels of TNF-α and IL-6 vary highly between newborns during sepsis." (PMID 38562936, 2024). "Although pediatric data are few, evidence on the role of IL-6 in neonates with sepsis is promising." (PMID 38254697, 2024). "The present study shows that IL-6 could be useful as a marker in the follow-up of patients with sepsis and their response to intervention during the early days of their ICU stay." (PMID 39589972, 2024).